SH3BGRL (SH3 domain binding glutamate rich protein like)
Diseases named in the same sentence as SH3BGRL in open-access papers:
SH3BGRL is named in the same sentence as 21 diseases in open-access papers, as found by Europe PMC text mining. Sharing a sentence is not in itself a finding about the gene and the disease. The quoted sentences say what the papers report.
breast carcinoma (7 papers, 2015 to 2025). "SH3BGRL has been linked to Parkinson’s disease, where higher expression is shown in cases compared to controls and is highly expressed in breast cancers." (PMID 39231932, 2024). "The expression level of SH3BGRL is also considered a diagnostic index of breast cancer." (PMID 33041670, 2020). "Once they are confirmed in the clinic, they can divide HER2-positive breast cancer into different subgroups, such as SH3BGRL, TGFBI methylation, and MEl-18." (PMID 37174034, 2023). "The DELs upstream of POU3F4 were also located downstream of SH3BGRL, which was reported to play a role in gastric cancer, acute myeloid leukemia and breast cancer." (PMID 35189936, 2022). "Previous results in breast cancer suggest SH3BGRL expression is correlated to worse prognosis." (PMID 40592808, 2025). "However, SH3BGRL has dual functions, being broadly upregulated in breast cancer but exhibiting low expression in AML progression." (PMID 37174034, 2023). "As SH3BGRL was predicted to bind with HER2, we then figured out the exact function of SH3BGRL in HER2-positive breast cancers and revealed that SH3BGRL can efficiently bind with HER2, which subsequently activates the downstream signals to enhance the HER2-targeted drug resistance." (PMID 37138798, 2023). "SH3BGRL, an adaptor protein, is upregulated in breast cancers and indicates its tumorigenic role." (PMID 37138798, 2023). "The binding of SH3BGRL to HER2 can also cause a conformational change in the receptor, leading to maintenance of unique tyrosine phosphorylation and promoting the extension of downstream signaling, thereby promoting the proliferation and survival of breast cancer cells." (PMID 37174034, 2023).
colorectal cancer (2 papers, 2020 to 2023). A primary or metastatic malignant neoplasm that affects the colon or rectum. "We previously uncovered that mouse SH3BGRL (mSH3BGRL) drives colorectal cancer metastasis through c-Src activation, but the human SH3BGRL function as a tumor suppressor in triple-negative breast cancers." (PMID 37138798, 2023). "Our previous results unmasked a novel role of mouse SH3BGRL (mSH3BGRL) in driving colorectal cancer metastasis through c-Src activation, but the inverse role of human SH3BGRL as a tumor suppressor." (PMID 32381043, 2020).
acute promyelocytic leukemia (1 paper, 2025). An aggressive form of acute myeloid leukemia (AML), characterized by arrest of leukocyte differentiation at the promyelocyte stage, due to a specific chromosomal translocation t(15;17) in myeloid cells. "SH3BGRL, which is underexpressed in acute promyelocytic leukemia, is known to enhance survival rates when activated by certain anti-tumor therapies." (PMID 39465506, 2025).
breast invasive carcinoma (1 paper, 2025). "We therefore examined SH3BGRL expression in breast invasive carcinoma and detected a significant higher expression of SH3BGRL in these cancers compared to non-diseased breast tissue." (PMID 40592808, 2025).
breast tumors (1 paper, 2020). "Therefore, SH3BGRL expression level could be considered as a diagnostic marker for breast tumor based on our results." (PMID 32381043, 2020). "In contrast, when knocking down the endogenous SH3BGRL in MDA-MB-453 cells, the tumorigenesis was significantly repressed, compared to the control cells, verifying the oncogenic role of SH3BGRL in breast tumor progression." (PMID 32381043, 2020). "Clinically, SH3BGRL is highly upregulated in breast tumors and squamous oral carcinoma, implying its possible tumor-promoting role in these contexts." (PMID 32381043, 2020). "In contrast, Silencing SH3BGRL or inhibiting its downstream signals efficiently induced apoptosis of breast tumor cells with HER2 and SH3BGRL doubly positive expression." (PMID 32381043, 2020). "Mechanistically, SH3BGRL promoted breast tumor cell proliferation and survival, while reduced the cell sensitivity to anti-tumor drugs, especially to the HER2-targeted drugs." (PMID 32381043, 2020). "However, SH3BGRL is observed to be broadly upregulated in breast tumors, including squamous oral carcinoma, among which only rare patients contain somatic mutation, such as R76C which can mimic the mouse SH3BGRL to enhance tumorigenesis and metastasis." (PMID 32381043, 2020). "However, accumulating evidence shows that SH3BGRL is highly upregulated in breast tumors, implying its possibly oncogenic role in breast cancer progression." (PMID 32381043, 2020). "Thus, SH3BGRL was verified to promote breast tumor cell cycle progression." (PMID 32381043, 2020). "In this study, we intend to thoroughly investigate the interaction between SH3BGRL and HER2 and unveil the exact novel role of SH3BGRL in HER2-positve breast tumors." (PMID 32381043, 2020). "Here we evidently characterized that SH3BGRL directly binds to HER2 via its motifs α1, α2 helixes and β3 sheet (core proline-rich PLPPQIF of SH3 domain) on cell membrane of breast tumor cells." (PMID 32381043, 2020). "Considering the adaptor character of SH3BGRL, this dual-sided effect might be attributed to the specific cell contexts in different tissues, including HER2 expression state in breast tumors." (PMID 32381043, 2020). "Consistently, we showed that SH3BGRL stimulated the AKT and ERK phosphorylation through the prolonged HER2 phosphorylation at Y1196, while silencing SH3BGRL abolished these effects, indicating the important effect of SH3GRL in HER2 Y1196 phosphorylation-dependent signaling in breast tumor cells." (PMID 32381043, 2020).
colon cancer (1 paper, 2026). "Deposited interactomes derived from HCT116 and HKe-3 colon cancer cell lines, as well as HEK293 cells include numerous proteins directly associated with the actin cytoskeleton in the datasets for SH3BGRL and SH3BGRL-2 26–28." (PMID 41565790, 2026).
Ductal Carcinoma (1 paper, 2020). "To investigate whether SH3BGRL is related to breast cancer progression, we analyzed the gene dataset, GSE15852 on breast cancer and observed that the SH3BGRL expression in Invasive Ductal Carcinoma (IDC) is obviously higher than in adjacent normal tissue (P = 0.034)." (PMID 32381043, 2020).
heart failure (1 paper, 2021). Inability of the heart to pump blood at an adequate rate to meet tissue metabolic requirements. "Even though it is unclear how SH3BGRL is directly involved in heart failure, SH3BGRL has evolved into a biomarker for identifying cardiotoxic agents and for diagnosing heart diseases." (PMID 34211507, 2021). "Furthermore, a clinical study showed that SH3BGRL was differentially expressed on the transcriptomic level between heart failure biopsies of non-ischemic cardiomyopathy patients and non-heart failure biopsies from unused cardiac transplant donors." (PMID 34211507, 2021).
liver cancer (1 paper, 2023). An epithelial or non-epithelial malignant neoplasm that arises from the liver. "To directly confirm the suppressive role of SH3BGRL in liver cancer progression, we approached the xenograft tumor model in nude mice." (PMID 37138798, 2023). "Here, we modulate SH3BGRL expression level in two liver cancer cells and conduct both in vitro and in vivo analyses of SH3BGRL in cell proliferation and tumorigenesis." (PMID 37138798, 2023). "Taken together, our results indicated that SH3BGRL functions as a tumor suppressor in liver cancer progression." (PMID 37138798, 2023). "Immunoblots also manifested the consistent SH3BGRL protein downregulation to its mRNA in tumor samples, while the basal level of autophagy in these liver cancers was also positively related to the expression of SH3BGRL." (PMID 37138798, 2023). "The relevance of SH3BGRL downregulation and liver cancer progression is also validated in patient samples." (PMID 37138798, 2023). "The semiquantitative PCR showed that the expression of SH3BGRL was downregulated in higher tumorigenic liver cancer cells (tumorigenic potential: LO2 < HepG2 < SMMC7721)." (PMID 37138798, 2023). "Meanwhile, this finding is consistent with the downregulation of SH3BGRL in liver cancers in our results and the public datasets." (PMID 37138798, 2023). "To verify the authentic relevance of SH3BGRL and autophagy in liver cancer, we collected 4 pairs of fresh liver tumor tissues and detected both mRNA and protein levels of SH3BGRL." (PMID 37138798, 2023). "The relevance of SH3BGRL downregulation in liver cancers and their progression is validated based on the large-scale tumor data." (PMID 37138798, 2023). "To test this hypothesis, we determine the physiological function of SH3BGRL in liver cancer cells by CCK-8 cell proliferation assay." (PMID 37138798, 2023). "Therefore, inhibition of the downstream-activated signaling pathways would be an alternative therapeutic strategy for SH3BGRL-downregulated liver cancers." (PMID 37138798, 2023). "However, here we found that SH3BGRL can clearly trigger the basal liver cancer cell autophagy in a nutrient-sufficient situation, indicating the existence of basal level autophagy and its physiological function in cell homeostasis maintenance." (PMID 37138798, 2023). "Overall, these results indicated that SH3BGRL might be a tumor suppressor in liver cancer progression." (PMID 37138798, 2023). "Here, we unveil the promoting role of SH3BGRL in basal autophagy occurrence and its suppressive function in liver tumor progression and indicate that SH3BGRL would be a potential prognosis biomarker of liver cancer." (PMID 37138798, 2023). "Therefore, we concluded that SH3BGRL may interact with ATG5 to prevent its ubiquitination-related degradation to enhance the consequent autophagy of liver cancer cells." (PMID 37138798, 2023). "Thus, our results further demonstrated that SH3BGRL enhances autophagy in hepatic cancer cells." (PMID 37138798, 2023). "Thus, we first uncover a suppressive role of SH3BGRL in liver cancer progression, which would be useful for liver cancer diagnosis and the SH3BGRL-depleted liver cancers by either targeting the activated downstream signaling or enhancing autophagic liver cancer cell death." (PMID 37138798, 2023). "Given that SH3BGRL could inhibit cell proliferation of liver cancer cells in starvation and the documentation of the interaction of SH3BGRL with ATG5, we tentatively checked whether SH3BGRL involves in the autophagy of liver cancer cells, as ATG5 plays a crucial role in autophagy." (PMID 37138798, 2023). "To demonstrate the exact function of SH3BGRL in liver cancer cell proliferation, we first overexpressed GFP-conjugated SH3BGRL (SH3BGRL) in both LO2 and HepG2 cell lines along with the empty vector (vector), respectively." (PMID 37138798, 2023). "Statistical analysis indicated that SH3BGRL is correlated to ATG5 expression level, but not ATG12 level in liver cancers." (PMID 37138798, 2023).
tumor (8 papers, 2012 to 2025). "Mouse and human SH3BGRL differ by a V108 mutation that can turn this protein from an oncogene into a tumour suppressor." (PMID 40592808, 2025). "SH3BGRL expression has been associated with cancer formation, promoting tumour initiation via c-src in murine cell lines, but also with tumour suppression, preventing tumour formation of various human cancer cells." (PMID 40592808, 2025). "Previous results indicate that human SH3BGRL functions as a tumor suppressor, and only the mutated ones promote tumor metastasis and progression." (PMID 32381043, 2020). "When SH3BGRL expression increased in the tumor environment, ADR resistance diminished, and treatment efficacy improved." (PMID 39465506, 2025). "The findings that in AML, SH3BGRL was both identified as a tumour promoter and a tumour suppressor, suggest that even factors within the same cancer can make SH3BGRL behave differently." (PMID 40592808, 2025). "On the other hand, overexpression of PFN1 in cells with high levels of SH3BGRL can counteract SH3BGRL-induced metastasis and tumor growth by upregulating PTEN and inhibiting the PI3K-AKT pathway." (PMID 38609844, 2024). "As expected, overexpression of SH3BGRL dramatically delayed the tumor formation induced by both LO2 and HepG2 cells through subcutaneous inoculation." (PMID 37138798, 2023). "Here, we first unveil that SH3BGRL binds with ATG5 and stabilize it to trigger autophagy initiation, indicating the crucial physiological function of SH3BGRL in cell homeostasis, while linking the autophagy and tumor progression together." (PMID 37138798, 2023). "Semiquantitative RT-PCR results showed that SH3BGRL was downregulated in all tumor tissues, compared to their corresponding adjacent normal counterparts." (PMID 37138798, 2023). "As expected, SH3BGRL knockdown dramatically increased the cell sensitivity to single Lapatinib or Herceptin, leading to the drastic tumor growth inhibition." (PMID 32381043, 2020). "Considering that the HER2-targeted therapy is not universally effective on HER2-possitive breast cancers, we further investigated if SH3BGRL overexpression can interfere with the anti-tumor drug sensitivity in breast cancer cells." (PMID 32381043, 2020). "We previously showed that mouse SH3BGRL promotes cancer metastasis as a novel c-Src activator, while human SH3BGRL, as an ortholog, suppresses tumor formation and metastasis." (PMID 32381043, 2020). "The scaffold protein SH3-domain-binding glutamic acid-rich protein-like protein (SH3BGRL) is indicated as a tumor suppressor in some cancers, but it is highly expressed in breast cancers." (PMID 32381043, 2020). "Nevertheless, here we uncovered that SH3BGRL-induced autophagy functions as a tumorigenic suppressor to inhibit cell proliferation and cell cycle, indicating that enhancement of SH3BGRL depletion tumor with autophagy agonists to induce high-level autophagy would be beneficial to therapy." (PMID 37138798, 2023). "Conversely, knockdown of SH3BGRL markedly enhanced the tumor formation of both tumor cells." (PMID 37138798, 2023). "Recent evidence indicates that SH3BGRL acts as either a tumor metastasis suppressor or a tumor promoter, but the exact role and molecular mechanism of SH3BGRL in liver tumor progression remain unknown." (PMID 37138798, 2023). "However, a clinical study demonstrated that SH3BGRL is highly expressed in breast tumors and squamous oral carcinomas, indicating its possible tumor-facilitating function." (PMID 37138798, 2023). "Therefore, Targeting SH3BGRL or its downstream signaling would be a promising and effective strategy, which is also validated by our xenograft tumor therapies." (PMID 32381043, 2020).
tumor (continued). "qRT-PCR and western blot analysis showed that, upon ALKBH5 silencing in tumor tissues, ALKBH5 and TUG1 were decreased, while SH3BGRL expression was upregulated (P < 0.01), suggesting that ALKBH5 silencing suppresses AML cell drug resistance to ADR in vivo." (PMID 39465506, 2025). "The tumor promoters BASP1, GPC1, PSAT1 and SH3BGRL are reported to be typically expressed in macrophages by the Expression Atlas." (PMID 32466393, 2020). "Quantitative expression analysis showed that SH3BGRL and p-HER2 (Y1196) expression were both significantly higher in tumor tissues than those in the adjacent normal tissues." (PMID 32381043, 2020). "Mechanistically, SH3BGRL binds with ATG5 and stabilizes it to drive the basal liver cell autophagy through inhibition of Src and its downstream ERK and AKT signaling pathways that generally lead to tumor cell survival and proliferation." (PMID 37138798, 2023). "But both SH3BGRL and PCBP1 function as tumor suppressors with their overexpression, which challenges which type of autophagy is triggered or inhibited for tumor suppression or tumor promotion, and what is the biomarker to judge the eventual function of the dual autophagy effect in tumorigenesis?" (PMID 37138798, 2023). "We found a large down-regulation of SH3BGRL2 mRNA levels and even though the other two family members, SH3BGRL and SH3BGRL3, were not significantly down-regulated both showed lower expression in tumours (−1.7 and −3.2 fold respectively) indicating that the whole family may be decreased in tumours." (PMID 22530001, 2012).
cancer (7 papers, 2015 to 2025). A tumor composed of atypical neoplastic, often pleomorphic cells that invade other tissues. "Our results showed that high expression of SH3BGRL was associated with a better survival in all cancers." (PMID 40592808, 2025). "Similarly, high SH3BGRL expression can both be associated with a better survival or with a reduced survival of cancer patients." (PMID 40592808, 2025). "SH3BGRL would be a pivotal therapy target and a diagnostic marker for SH3BGRL and HER2 doubly positive cancers." (PMID 32381043, 2020). "In contrast, low SH3BGRL expression is related to AML progression, indicating the dual functions of SH3BGRL in cancer progression." (PMID 32381043, 2020). "This phenomenon of SH3BGRL-mediated inhibition of cell proliferation and arrest of the cell cycle can be strengthened under autophagic starvation conditions, which provides an alternative therapy for relevant cancers." (PMID 37138798, 2023). "Furthermore, data from TCGA Pan-Cancer Clinical Data Resource showed that high SH3BGRL expression was related to poor progression-free interval (PFI)." (PMID 32381043, 2020). "But the function of SH3BGRL in other types of cancers is largely unknown." (PMID 37138798, 2023). "The SH3 Domain Binding Glutamate Rich Protein Like (SH3BGRL) is located within the extracellular vesicles and as a scaffold protein it mediates many protein–protein interactions; however, its role in cancer is still largely undefined." (PMID 36945054, 2023). "SH3BGRL expression is higher in carcinomas compared to expression in non-diseased epithelial tissues." (PMID 40592808, 2025). "SH3BGRL expression in all cancers is higher than in a non-diseased population." (PMID 40592808, 2025).
infection (2 papers, 2022). The state of being infected such as from the introduction of a foreign agent such as serum, vaccine, antigenic substance or organism. "MDBK cells, CRIB-1 cells or the respective cells expressing ADAM17 or SH3BGRL were infected with an MOI of 0.001 and analyzed 72 h post infection to determine the amount of fluorophore positive cells in a flow cytometer." (PMID 35215974, 2022).
SH3BGRL also shares sentences with these, for which no sentence is quoted: Parkinson disease (2 papers); acute myeloid leukemia (1); gastric cancer (1); heart diseases (1); hematological disease (1); ischemic cardiomyopathy (1); prostate carcinoma (1); triple-negative breast carcinoma (1); X-linked disease (1).